KRT7 (keratin 7)
Diseases named in the same sentence as KRT7 in open-access papers (continued):
Sharing a sentence is not in itself a finding about the gene and the disease.
bone metastasis (2 papers, 2020 to 2022). Transfer of a neoplasm from its primary site to bones. "We found that the intensity of KRT7 expression in benign peri-tumoral glands was associated with bone metastasis-free survival and PC-specific mortality." (PMID 35406395, 2022). "Remarkably, KRT7-high expression was significantly associated with an increased risk of developing bone metastasis (28 events, log-rank = 4.07, p = 0.044) and an increased risk of PC-associated death at 15 years (15 events, log-rank = 3.98, p = 0.046)." (PMID 35406395, 2022). "Remarkably, a low KRT7 staining was associated with a 94% negative predictive value for bone metastasis onset." (PMID 35406395, 2022). "Low KRT7 staining was indicative of a good prognosis and was associated with a negative predictive value of 94% for bone metastasis onset." (PMID 35406395, 2022). "KRT7-high expression (>80th percentile) was also found to be statistically significant in a multivariable model (HR = 2.907, p = 0.014) and identified as an independent marker to predict the onset of bone metastasis, but with lower predictive capacity than the Gleason score (HR = 27.014, p < 0.001)." (PMID 35406395, 2022). "The KRT7 expression on benign cores from prostate biopsies could help segregate patients and recommend low-KRT7 patients for active surveillance, while proposing radical treatment to high-KRT7 patients (MFI of KRT7 > 80th percentile) due to a higher risk of the onset of bone metastasis." (PMID 35406395, 2022).
follicular carcinomas (2 papers, 2014 to 2017). "The biopsy of the lesion demonstrated neoplastic cells stained positive for thyroglobulin, thyroid transcription factor-1, and cytokeratin-7, consistent with metastatic follicular thyroid cancer." (PMID 26425617, 2014).
Lymphatic Metastasis (2 papers, 2022 to 2023). Transfer of a neoplasm from its primary site to lymph nodes or to distant parts of the body by way of the lymphatic system. "According to the comprehensive analysis of IHC scores and clinicopathological characteristics, high expression of KRT7 was significantly associated with higher stage, lymphatic metastasis, and shorter OS time." (PMID 35974300, 2022).
mesonephric neoplasm (2 papers, 2021 to 2025). An epithelial neoplasm of the female reproductive system arising from mesonephric remnants. "Most tumors were positive for cytokeratin-7 (8/9), EMA (9/9), estrogen and progesterone receptor (9/9), CD10 (7/9, including a luminal pattern reminiscent of mesonephric neoplasms), nuclear β-catenin (8/9), and CDX2 (8/9)." (PMID 38418687, 2025).
NUT carcinoma (2 papers, 2022 to 2025). "Both cases diffusely expressed p63 and NUT consistent with classic NUT carcinoma, but one case also showed patchy cytokeratin 7, Napsin-A, and TTF1 expression in the micropapillary component, consistent with some divergent adenocarcinoma differentiation." (PMID 34997561, 2022).
parotid gland cancer (2 papers, 2012 to 2019). A primary or metastatic malignant neoplasm involving the parotid gland. "Histopathology confirmed the diagnosis of a parotid gland carcinoma and immunohistochemical markers showed that the tumor cells express cytokeratin, epithelial membrane antigen, cytokeratin 7, smooth muscle actin, P63, CEA, and S100." (PMID 23008793, 2012).
prostate tumors (2 papers, 2020 to 2022). "Thus, KRT7-positive benign epithelial cells surrounding prostate tumors may be also involved in functional interactions with immune cells." (PMID 35406395, 2022).
pseudomyxoma peritonei (2 papers, 2022 to 2023). An appendix cancer that is characterized by progressive accumulation of mucus-secreting tumor cells within the abdomen and pelvis. "Ultrasound-guided percutaneous biopsy of an abdominal wall lesion was executed and histopathological examination identified localization of pseudomyxoma peritonei, with immunohistochemical staining being positive for cytokeratin 20 (CK-20) and CDX-2 and negative for cytokeratin 7 (CK-7)." (PMID 35538541, 2022).
pulmonary neoplasms (2 papers, 2025 to 2026). "Negative staining for cytokeratin 7 (CK7), cytokeratin 20 (CK20), caudal-type homeobox transcription factor 2 (CDX2), and thyroid transcription factor 1 (TTF-1) helped exclude primary gastric, gastrointestinal, and pulmonary neoplasms." (PMID 41769517, 2026).
salivary carcinoma (2 papers, 2015 to 2024). "According to HE and immunohistochemistry, it was diagnosed as salivary carcinoma because of positive expression of α-SMA, negative expression of cytokeratin 7 and thyroglobulin." (PMID 25868857, 2015).
small bowel cancer (2 papers, 2021 to 2024). "Immunostaining was negative for Cytokeratin 7 (CK7), positive for Cytokeratin 20 (CK20) and Special AT-Rich Sequence-Binding Protein 2 (SATB2), and negative for estrogen receptor (ER) and Paired Box Gene 2 (PAX2), leading to a diagnosis of metastatic recurrence of small bowel cancer." (PMID 39156866, 2024).
Warthin tumor (2 papers, 2023 to 2026). An adenoma characterized by an oncocytic, often papillary, epithelial component, dense lymphoid stroma, and cystic spaces. "Cytokeratin 7 expression in Warthin tumors was predominantly luminal." (PMID 42054169, 2026).
adenopathies (1 paper, 2021). "Tissue biopsies from the primary tumor and right groin adenopathies revealed an adenocarcinoma, with positive cytokeratin-7 (CK7), epithelial membrane antigen (EMA), thyroid transcription factor-1 (TTF-1) immunohistochemistry (IHC), and negative cytokeratin-20 (CK20) staining." (PMID 33608032, 2021).
alcohol (1 paper, 2025). "These clinical findings further implied the tumour promotion effect of the ALB+KRT7+ epithelial cells in alcohol‐related HCC." (PMID 39834100, 2025). "Coherently, we observed more immunosuppressive‐like tumour environment in alcohol‐related HCC with high ALB+KRT7+ population abundance." (PMID 39834100, 2025).
Anal fistula (1 paper, 2015). An abnormal connection between the epithelialised surface of the anal canal and the perianal skin. "In immunohistochemical staining, both the rectal lesion and the anal fistula stained negative (−) with antibodies to cytokeratin 7 (CK7) and positive (+) with antibodies to cytokeratin 20 (CK20)." (PMID 26943447, 2015).
atrophic gastritis (1 paper, 2024). "In the current study, Krt7 was also increased at the transcriptional level in cases of atrophic gastritis." (PMID 38059647, 2024).
cholesteatoma (1 paper, 2014). A pathologic process characterized by the proliferation of keratinizing squamous epithelium resulting in the accumulation of keratin and cells in the middle ear and/or mastoid. "Other keratins had increased levels of expression in non-cholesteatoma tissues: KRT76, 79 (Tympanic membrane), KRT15 (EACS), and KRT7, 8, 18, 19 (Mucosa)." (PMID 25093596, 2014).
fibrolamellar carcinoma (1 paper, 2018). "Fibrolamellar carcinoma has a distinctive morphology and immunophenotype, including cytokeratin 7 and CD68 co-expression." (PMID 28862261, 2018).
ischemia (1 paper, 2025). A hypoperfusion of the BLOOD through an organ or tissue caused by a PATHOLOGIC CONSTRICTION or obstruction of its BLOOD VESSELS, or an absence of BLOOD CIRCULATION. "Several periportal keratin 7 (K7)-positive intermediate hepatocytes were seen, indicative of mild chronic cholestasis, while few centrilobular K7-positive hepatocytes were also present, indicative of mild ischemia." (PMID 40507741, 2025).
keloid (1 paper, 2022). An irregularly shaped, elevated mark on the skin caused by deposits of excessive amounts of collagen during wound healing. "In keloids Keratin 7 (KRT7) was increased 3.52‐fold compared to normal keratinocytes." (PMID 36483731, 2022).
mammary Paget disease (1 paper, 2006). A malignant neoplasm in which there is infiltration of the skin overlying the breast by neoplastic large cells with abundant pale cytoplasm and large nuclei with prominent nucleoli (Paget cells). "Among the cytokeratins, cytokeratin 7 and 20 are sensitive but not specific markers of mammary Paget's disease, and most cases are labelled by EMA antibody." (PMID 16899115, 2006).
mastitis (1 paper, 2022). Inflammation of breast tissue during lactation or postpartum due to an obstructed duct or infection. "Other noteworthy genes (RHPN2, ACSS2, RHOU, and KRT7) showing lower expression in cows with mastitis have critical roles in biological pathways, cellular process, fatty acid synthesis, and metabolism." (PMID 35723402, 2022).
meningioma (1 paper, 2020). A generally slow growing tumor attached to the dura mater. "The focus within the meningioma stained positive for cytokeratin 7 (CK7) and thyroid transcription factor 1 (TTF-1) and negative for CK5/6, p63, CD56, and synaptophysin." (PMID 33126391, 2020).
odontogenic keratocysts (1 paper, 2022). "Furthermore, the expression of keratin-7 was found in the superficial layers of the well-differentiated RC, but was significantly lower in the less differentiated odontogenic keratocysts, concluding that the existence of this keratin is correlated with the degree of differentiation of these cysts." (PMID 35419179, 2022).
ovarian serous cystadenocarcinoma (1 paper, 2021). A malignant serous cystic epithelial neoplasm arising from the ovary. "Using CPTAC protein expression from the TCGA Ovarian Serous Cystadenocarcinoma dataset (n = 274), we observed that protein expression of E-CADH was negatively correlated to markers of EMT, whereas KRT7 and 19 were not correlated to markers of EMT." (PMID 34070214, 2021).
salivary duct carcinoma (1 paper, 2021). An aggressive, high grade adenocarcinoma that arises from the salivary glands. "The tumor cells expressed both cytokeratin 7 (CK7) and androgen receptor, confirming the diagnosis of salivary duct carcinoma." (PMID 33859885, 2021).
Stillbirth (1 paper, 2016). Death of the fetus in utero after at least 22 weeks of gestation. "The median trophoblast area (measured as cytokeratin-7 positive area) was increased in stillbirths attributed to infection and FGR." (PMID 26865834, 2016).
Ta (1 paper, 2005). "By Western blotting analysis we found that the KRT7 protein level indeed was increased in Ta tumours (N=7)." (PMID 16265353, 2005). "We evaluated the KRT7 protein expression simultaneously in tumour tissue, plasma, urine supernatant, and urine pellet from four individuals diagnosed with Ta tumours." (PMID 16265353, 2005). "Among the mostly changed genes between normal bladder and Ta tumours, we found genes related to the cytoskeleton (keratin 7 and syndecan 1), and transcription (high mobility group AT-hook 1)." (PMID 16265353, 2005). "To investigate whether KRT7 mRNA levels correlate with the protein levels, we simultaneously measured KRT7 gene expression (by microarrays) and protein expression (by Western blotting) of four Ta tumours." (PMID 16265353, 2005). "Thus, the observed increase in KRT7 protein (and mRNA) could reflect cancer cell enrichment in Ta tumour biopsies, and might not only be a result of KRT7 overexpression." (PMID 16265353, 2005). "Consistent with the literature, we found members of the cytokeration family, especially KRT7, but also KRT8 highly expressed in Ta tumours." (PMID 16265353, 2005).
urethral carcinoma (1 paper, 2025). "The urethral carcinoma was positive for KRT5 and KRT7, consistent with urothelial origin." (PMID 39806204, 2025).
Wolffian tumors (1 paper, 2022). "While MLA shows diffuse and strong membranous cytokeratin 7 (CK7) immunoreactivity, Wolffian tumors are usually focally positive for CK7." (PMID 35204416, 2022).
ZIKV infection (1 paper, 2025). "Most isolated cells were cytokeratin-7 positive with a proportion also displaying ZIKV-E-Ag or dsRNA positive staining localised to the cytoplasm, as expected for ZIKV infection." (PMID 40253335, 2025).
tumor (989 papers, 2002 to 2026). "High levels of KRT7 are associated with higher tumor grades, advanced stages, and poor prognoses, likely due to its role in promoting proliferation and EMT via the TGF-beta/SMAD2/3 signaling pathway." (PMID 41465326, 2025). "These together implicated possible tumour initiation or promotion roles of ALB+KRT7+ EPCs‐derived ALD organoids." (PMID 39834100, 2025). "The expression of KRT7 correlates with the tumor growth and metastasis and the levels of the EMT-associated transcription factors (SNAI1, SNAI2, TWIST1, TWIST2), and the mesenchymal markers, such as fibronectin, and vimentin (VIM)." (PMID 39329988, 2024). "KRT7 expression has a role in epithelial–mesenchymal transition and its dysregulation has been highly associated with various types of cancers and tumor progression." (PMID 37239418, 2023). "KRT7 upregulation in MSC cultures was associated with exposure to tumor-associated factors and progression towards carcinoma-associated fibroblast-like phenotype." (PMID 36140831, 2022). "Expression of KRT7 has been significantly associated with immune infiltration of tumor immune cells and immunomodulators in other carcinomas." (PMID 35406395, 2022). "Other genes identified in this study as over-expressed in CIN3/AIS lesions compared to normal cervical tissue are also associated with tumor development (KRT7, TNFRSF18 and TNFRSF4)." (PMID 35008799, 2021). "Immunohistochemical analyses of Oct4A KD tumor xenografts demonstrated a significant loss of cytokeratin 7 (CK7), Glut-1 as well as CD34 and CD31 compared to vector control cell-derived xenografts." (PMID 27390927, 2016). "Alcohol metabolites will inevitably induce accumulation of gene mutations in liver cells, once ALB+KRT7+ population transform to malignant cells due to gene mutation or other malignant cells appear, the existing ALB+KRT7+ populations promote the tumour initiation and progression." (PMID 39834100, 2025). "Furthermore, we observed that the genes associated with tumour poor prognosis, KRT7 and COL13A1,65, 66, 67 exhibited chromatin accessibility in C1 and C2." (PMID 39210544, 2024). "Moreover, we examined if recently identified Krt7+ subpopulations at the SCJ30 are significantly associated with higher tumor susceptibility." (PMID 31110179, 2019). "Interestingly, we observed that the presence of OvCa+/CD45– CTCs detected in protocol B was associated with low KRT5 and KRT7 gene expression levels in the paired primary tumor tissue samples." (PMID 29290959, 2017). "In addition to cytomorphological analysis, gene expression of tumor associated genes (Cytokeratin-18, Cytokeratin-19, Cytokeratin-20, Cytokeratin-7, EPCAM, MUC1, HER2, EGFR) and of leukocyte markers (e.g. CD45, CD68) was tested in enriched CTC fractions." (PMID 25862542, 2016). "Histologic evaluation revealed poorly cohesive tumor cells infiltrating the lamina propria, and immunohistochemistry was positive for cytokeratin 7, GATA3, and estrogen receptor, confirming metastatic breast carcinoma." (PMID 41871938, 2026). "KRT7 belongs to the family of genes known as keratins, which are highly expressed in numerous types of cancer and facilitate tumor progression." (PMID 41383978, 2026). "Subsequent surgical excision confirmed an oncocytic lipoadenoma, a biphasic tumor comprising mature adipose tissue and cytokeratin 7-positive oncocytic epithelial nests." (PMID 42122068, 2026). "Thereafter, we detected an elevated expression of several tumor cell‐associated markers, including S100P, KRT17, KRT16, KRT7, and LY6D, as previously reported." (PMID 41164952, 2026). "The tumor cells showed positivity for cytokeratin 7 (CK7) and CEA, indicating glandular differentiation." (PMID 40351999, 2025).
tumor (continued). "Our analysis showed that ALB+KRT7+ epithelium in advanced alcohol‐related cirrhosis had increased Wnt activities, and inhibition of Wnt signalling can prevent the tumour promotion effect of ALB+ KRT7+ epithelium in organoid and murine models." (PMID 39834100, 2025). "Tumor cells were positive for cytokeratin (CK), cytokeratin 7 (CK7), estrogen receptor (ER) and progesterone receptor (PR), but negative for Wilms' tumor 1 (WT‐1)." (PMID 41152971, 2025). "Immunohistochemical stains (IHC) showed the tumor positive for cytokeratin 7 (CK7) and CK 19, and weakly positive for paired box gene 8 (PAX8)." (PMID 40182334, 2025). "Clusters 20 and 12 from the original UMAP (Figure A4b) were identified as PDAC tumor cells based on their expression of marker genes, including Sox9, Krt7, Krt19, or Epcam." (PMID 39857986, 2025). "Collectively, our findings strongly suggested that ALB+KRT7+ EPCs originated organoids promoted tumour growth via Wnt/β‐catenin signalling." (PMID 39834100, 2025). "In this case, we analyzed the expression of tumor cells by various IHC methods and special stains, with a review of the literature, the cytokeratin 7 (CK7) and mucin 1 (MUC-1) expression patterns of IP tumor cells contribute to pathological diagnosis." (PMID 40013097, 2025). "In an immunohistochemistry (IHC) study, the tumor stained positive for calcitonin, cytokeratin 7 (CK7), thyroid transcription factor 1 (TTF1), and synaptophysin with an intermediate Kiel 67 (Ki-67) index." (PMID 40698208, 2025). "Immunohistochemistry revealed that the tumor cells were positive for cytokeratin 7 (CK7), Ber-EP4, epithelial membrane antigen (EMA), and thyroid transcription factor-1 (TTF-1)." (PMID 40922881, 2025). "As expected, there was minimal staining for Keratin-7, a marker used to detect differentiated tumor cells." (PMID 40371051, 2025). "On histopathological evaluation, the immunohistochemical analysis showed that tumor cells exhibited positive staining for cytokeratin 7 (CK7), lymphoid enhancer-binding factor 1 (LEF1), calponin, and s100 (focal) while negative for GATA3 and TTFl." (PMID 40078247, 2025). "The Tumor-0 subcluster comprised the majority of cells, with upregulated genes typical of tumor markers, such as Ccnd1, Cd44, Krt7 and Plau." (PMID 41332581, 2025). "The consistent use of immunohistochemical markers, such as calretinin and cytokeratin 7, was crucial in distinguishing this rare tumor from other malignancies." (PMID 39860304, 2025). "In human CCA specimens, we detected a lower positivity for the epithelial marker cytokeratin 7 (CK7) in nerve-infiltrating CCA cells with respect to the tumor mass." (PMID 38474330, 2024). "The characteristic marker FGA of the liver was mainly expressed in hepatocyte, the main marker KRT7 of tumor cells was mainly expressed in malignant cells, and we were excited to find that GJB2 was mainly expressed in malignant cells." (PMID 39162005, 2024). "The epithelial cell marker genes EPCAM, KRT19, and KRT7 were used to annotate tumor cells that were further verified copy number variations." (PMID 39474422, 2024). "Immunostains performed on the tumor cells within the cell block were positive for cytokeratin 7 (CK7), TTF-1, napsin-A, and weak patchy for paired-box gene 8 (PAX8)." (PMID 39318937, 2024). "Our data show that in human intrahepatic CCA specimens with documented PNI, nerve-infiltrating CCA cells display positivity of the epithelial marker cytokeratin 7, lower with respect to the rest of the tumor mass." (PMID 38474330, 2024). "The tumor cells were immunohistochemically positive for cytokeratin 7 (CK7), gross cystic disease fluid protein 15, GATA-binding protein 3, human epidermal growth factor receptor 2, and androgen receptor and negative for CK20, CK5, p63, S100, and CDX2." (PMID 39310547, 2024).